SNHG14 (small nucleolar RNA host gene 14)
Diseases named in the same sentence as SNHG14 in open-access papers (continued):
Sharing a sentence is not in itself a finding about the gene and the disease.
osteoporosis (4 papers, 2020 to 2025). A condition of reduced bone mass, with decreased cortical thickness and a decrease in the number and size of the trabeculae of cancellous bone (but normal chemical composition), resulting in increased fracture incidence. "SNHG14 overexpression elevated bone mineral density and bone trabecular number, and alleviated osteoporosis progression in vivo." (PMID 37925525, 2023). "SNHG14 is known to be declined in BMSCs from patients with osteoporosis, and it promotes OD of BMSCs by targeting the miR-185-5p/WISP2 axis." (PMID 36644009, 2023). "In conclusion, SNHG14 activated autophagy via regulating miR-493-5p/Mef2c axis to alleviate osteoporosis progression." (PMID 37925525, 2023). "Similar to previous studies, we identified that lncRNA SNHG14 was upregulated but miR-2861 was downregulated in serum and hMSCs from patients with osteoporosis." (PMID 32770994, 2020). "We found that the expression of SNHG14 was enhanced, while the expression of miR-2861 was suppressed in serum and hMSCs from patients with osteoporosis." (PMID 32770994, 2020). "A negative relationship was established between the expression of SNHG14 and miR-2861 in serum of osteoporosis group." (PMID 32770994, 2020). "SNHG14 regulates the expression of Mef2c and activates autophagy through miR-493-5p, promoting osteogenic differentiation of BMSCs and consequently alleviating osteoporosis development." (PMID 37925525, 2023). "Bone histomorphometry changes were evaluated to analyze SNHG14’roles in osteoporosis in vivo." (PMID 37925525, 2023). "In short, SNHG14 activated autophagy via regulating miR-493-5p/Mef2c axis to alleviate osteoporosis progression, which might provide a new molecular target for osteoporosis treatment." (PMID 37925525, 2023). "It has demonstrated that SNHG14 by regulating miR-493-5p/Mef2c-mediated autophagy activation, leading to the promotion effect on osteogenic differentiation of BMSCs, thereby improving osteoporosis progression." (PMID 37925525, 2023). "The finally data showed that SNHG14 targeted miR-493-5p/Mef2c axis to regulate autophagy activation, resulting the promotion effect in osteogenic differentiation of BMSCs, suggesting SNHG14 might be an effective target for osteoporosis treatment." (PMID 37925525, 2023). "Therefore, we hypothesized that SNHG14 regulated the expression of Mef2c and activated autophagy through miR-493-5p, promoting osteogenic differentiation of BMSCs, thus alleviating osteoporosis development." (PMID 37925525, 2023). "Compared to participants without osteoporosis (n = 20), the expression levels of SNHG14 in serum and hMSCs of osteoporosis patiens (n = 20) were greatly elevated." (PMID 32770994, 2020). "Compared to non-osteoporosis participants, the expression levels of SNHG14 in serum and hMSCs of osteoporosis patients were greatly elevated." (PMID 32770994, 2020). "In addition, a negative relationship between the expression of SNHG14 and miR-2861 in the serum of the osteoporosis group was observed." (PMID 32770994, 2020). "However, it was not clear whether SNHG14 participated in the progression of osteoporosis through targeting miR-493-5p." (PMID 37925525, 2023).
Cerebral ischemia (3 papers, 2019 to 2022). Restriction of arterial blood supply to the brain associated with insufficient oxygenation to support the metabolic requirements of the tissue. "Long non-coding RNA (lncRNA) small nucleolar RNA host gene 14 (SNHG14) is associated with cerebral ischemia–reperfusion (CI/R) injury." (PMID 32912324, 2020). "SNHG14 promotes the expression of Atg5 and Beclin 1 by sponging miR-30b-5p, thereby activating autophagy and aggravating cerebral ischemia-reperfusion injury." (PMID 36275741, 2022). "To explore the molecular mechanism of SNHG14 in cerebral ischemia–reperfusion injury, we examined the expression of miR-182-5p and BNIP3 in the OGD/R-induced HT22 cells." (PMID 32912324, 2020). "Deletion of SNHG14 attenuates cerebral ischemia in MCAO model mice." (PMID 36275741, 2022).
Parkinson disease (3 papers, 2019 to 2021). A progressive degenerative disorder of the central nervous system characterized by loss of dopamine producing neurons in the substantia nigra and the presence of Lewy bodies in the substantia nigra and locus coeruleus. "Snhg14 is highly expressed in Parkinson’s disease, and silencing Sngh14 mitigated dopaminergic neuron injury by downregulating a-syn by targeting miR-133b." (PMID 34722547, 2021).
prostate carcinoma (3 papers, 2020 to 2022). A carcinoma that arises from epithelial cells of the prostate gland. "As an oncogene in prostate cancer, SNHG14 contributes to the progression of prostate cancer by sponging miR-613." (PMID 32912324, 2020).
renal cell carcinoma (3 papers, 2019 to 2021). "SP1-induced up-regulation of lncRNA SNHG14 was demonstrated to promote the metastatic potential of cell renal cell carcinoma cells." (PMID 32396871, 2020). "Additionally, up-regulation of SNHG14 boosts cell migration and invasion in renal cell carcinoma." (PMID 31889897, 2019).
Sepsis (3 papers, 2021 to 2025). Sepsis is defined as life-threatening organ dysfunction caused by a dysregulated host response to infection. "Analyses of plasma samples revealed that individuals afflicted by sepsis-associated AKI exhibited higher expression of the lncRNA small nucleolar RNA host gene 14 (SNHG14)." (PMID 38275604, 2024). "The role of SNHG14 in sepsis-induced AKI has been highlighted in several studies." (PMID 40657645, 2025). "Consistently, SNHG14/miR-495-3p/HIPK1 may represent a potential therapeutic axis for the treatment of sepsis-induced AKI." (PMID 38275604, 2024). "Similarly, lncRNA SNHG14 was overexpressed in septic patient plasma with AKI, and SNHG14 could interact with miR-495-3p and exert influence on cell apoptosis, proliferation, and inflammatory response, thereby exacerbates sepsis-induced AKI." (PMID 34630395, 2021).
lymph node metastasis (2 papers, 2021 to 2022). "It was suggested that SNHG14, miR-211-3p and ESM1 in BCa were linked with TNM stage, tumor invasion stage and lymph node metastasis, but was not with gender, age, pathological grade or tumor size." (PMID 33482820, 2021).
metastasis (2 papers, 2021). The spread or migration of cancer cells from one part of the body (where they first appeared) to another. "Moreover, the expression level of SNHG14 was closely associated with multiple clinicopathological characteristics such as prognosis, tumor differentiation, TNM stage, and lymph node metastasis." (PMID 34631721, 2021).
Obesity (2 papers, 2021 to 2024). Accumulation of substantial excess body fat. "SNHG14 is involved in various biological processes, such as regulating neuronal cell apoptosis and inflammation, obesity‐induced endoplasmic reticulum stress in adipocyte, mesenchymal stem cell osteogenesis, cancer cell proliferation, and epithelial‐mesenchymal transition." (PMID 38751373, 2024).
Prader-Willi syndrome (2 papers, 2021 to 2025). "Our study presents the clinical and genetical features of the first patient with a denovo 15q11.2 interstitial duplication on the maternal allele (inv Dup15q) that mimics a milder Prader-Willi syndrome probably due to an atypical disruption of the SNHG14 gene." (PMID 34007283, 2021).
thyroid cancer (2 papers, 2025). "similarly reported significant upregulation of SNHG14 in thyroid cancer tissues, accompanied by decreased miR-433-3p levels." (PMID 41234719, 2025). "Silencing SNHG14 significantly inhibited the proliferation, invasion, and migration of thyroid cancer cells (TPC1)." (PMID 41234719, 2025). "In summary, SNHG14 is widely overexpressed in thyroid cancer and promotes cell proliferation, invasion, metastasis, and suppresses apoptosis by regulating multiple miRNA-related pathways, including miR-93-5p and miR-433-3p." (PMID 41234719, 2025). "Its overexpression is closely associated with clinical malignant phenotypes, suggesting that SNHG14 not only plays a crucial role in the initiation and progression of thyroid cancer but may also serve as a potential molecular target and prognostic biomarker." (PMID 41234719, 2025). "Sang's study on the biological functions of lncRNA SNHG14 in thyroid cancer cell development by targeting miR‐206 reveals that SNHG14 upregulation elevates miR‐206 levels, impacting the proliferation, invasion, apoptosis and EMT of thyroid cancer cells." (PMID 40521987, 2025). "In thyroid carcinoma, certain SNHG family members (e.g., SNHG7, SNHG15, SNHG12, SNHG14) have been reported as oncogenes, while others (e.g., SNHG3, SNHG5) may function as tumor suppressors—a discrepancy warranting further investigation." (PMID 41234719, 2025).
acute myeloid leukemia (1 paper, 2021). Acute myeloid leukemia (AML) is a group of neoplasms arising from precursor cells committed to the myeloid cell-line differentiation. "Lnc-CCDC26, lnc-DARS-AS1 and lnc-SNHG14 play oncogenic roles in childhood acute myeloid leukemia (AML)." (PMID 34112247, 2021).
acute respiratory distress syndrome (1 paper, 2021). Progressive and life-threatening pulmonary distress in the absence of an underlying pulmonary condition, usually following major trauma or surgery. "For example, MALAT1 was reportedly related to acute respiratory distress syndrome related to lung injury, downregulation of SNHG14 had protective effects against LPS-induced ALI, and CASC2 improved ALI by reducing lung epithelial cell apoptosis." (PMID 33506021, 2021).
Alzheimer disease (1 paper, 2020). A progressive, neurodegenerative disease characterized by loss of function and death of nerve cells in several areas of the brain leading to loss of cognitive function such as memory and language. "It is currently known that Snhg14 is a lncRNA that targets snoRNA, and Mir1898 targets 50 differentially expressed genes which are involved in pathways such as Ras signaling, Rap1 signaling, MAPK signaling, Ubiquitin mediated proteolysis, Tight junction and Alzheimer’s disease to name a few." (PMID 33142695, 2020).
atherosclerosis (1 paper, 2024). A disease characterized by the build-up of fatty material and calcium deposition in the arterial wall resulting in partial or complete occlusion of the arterial lumen. "Consistent with our findings, SNHG14 have been reported to promote the proliferation of various cells, such as tumor cells, trophoblast cells, and atherosclerosis cells." (PMID 38751373, 2024).
injury (1 paper, 2021). Damage inflicted on the body as the direct or indirect result of an external force, with or without disruption of structural continuity. "Small nucleolar RNA host gene 14 (SNHG14) may contribute to the inflammatory response to CIR by regulating miR-136 expression, so as to aggravate its nerve injury." (PMID 34868528, 2021).
ischemia (1 paper, 2019). A hypoperfusion of the BLOOD through an organ or tissue caused by a PATHOLOGIC CONSTRICTION or obstruction of its BLOOD VESSELS, or an absence of BLOOD CIRCULATION. "Taken together, our study demonstrated a novel lncRNA SNHG14/miR-136–5p/ROCK1 regulatory network in ischemia induce injury, providing a potential biomarker and therapeutic target for ischemia stroke." (PMID 30546117, 2019). "In our study, we also found interference of SNHG14 improve ischemia induced injury and inflammation in vitro and vivo." (PMID 30546117, 2019). "In conclusion, we illustrated that lncRNA SNHG14 was highly expressed in vivo and in vitro, and promoted neuronal damage and inflammation induced by ischemia injury." (PMID 30546117, 2019). "Finally, we demonstrated that SNHG14 participated in regulation of inflammation induced by I/R damage via regulation of miR-136–5p/ROCK1 axis and could be a new strategy for the treatment cerebral damage induced by ischemia." (PMID 30546117, 2019).
nasopharyngeal carcinoma (1 paper, 2023). A carcinoma arising from the nasopharyngeal epithelium. "The expression of SNHG14 is up-regulated in nasopharyngeal carcinoma (NPC)." (PMID 36810034, 2023).
pneumoconiosis (1 paper, 2025). An occupational lung disorder caused by inhalation of dust particles. "Currently, genome-wide association studies (GWAS) have identified a strong association between some common single-nucleotide polymorphisms (SNPs), such as small nucleolar RNA host gene 14 (SNHG14), desmoplakin (DSP), and laminin beta 1 (LAMB1), and pneumoconiosis." (PMID 40182855, 2025).
rheumatoid arthritis (1 paper, 2024). A chronic, systemic autoimmune disorder characterized by inflammation in the synovial membranes and articular surfaces. "Moreover, miR-17-5p seems to target MINK1, and SNHG14 counterplays this regulation in rheumatoid arthritis." (PMID 39727954, 2024).
Schaaf-Yang syndrome (1 paper, 2025). "This cluster comprises the MKRN3, NDN, MAGEL2, and SNHG14 genes, the loss of function of which contributes to Prader-Willi and Schaaf-Yang syndromes." (PMID 40877933, 2025).
schizophrenia (1 paper, 2021). A major psychotic disorder characterized by abnormalities in the perception or expression of reality. "In the same manner, 60 of 66 sites dEd in schizophrenia were concentrated in the TRIM9 and SNHG14 genes." (PMID 34535545, 2021).
scoliosis (1 paper, 2025). A congenital or acquired spinal deformity characterized by lateral curvature of the spine. "In our study, we observed that HLA DR on CD14+ CD16+ monocyte was associated with a reduced risk of scoliosis, and SNHG14, SNORA33, and NET1 shared the same variant with HLA DR on CD14+ CD16+ monocyte." (PMID 40177401, 2025). "SNHG14, SNORA33, NET1, and SNORD100 shared the same variant with HLA DR on CD14+ CD16+ monocyte which could decrease the risk of scoliosis." (PMID 40177401, 2025).
tumor (48 papers, 2018 to 2025). "The major mechanism underlying the tumor-promoting function of SNHG14 is to regulate target genes via competing with miRNAs." (PMID 34631721, 2021). "High expression of SNHG14 was associated with poor tumour differentiation, advanced TNM stage and nodal metastasis." (PMID 31513352, 2019). "SNHG14 is a significant promoter of tumour progression, with high expression levels seen nearly across all cancer types, highlighting its crucial role in oncogenesis." (PMID 40521987, 2025). "SNHG14 is able to inhibit the body's immune response to tumor, thereby promoting tumor immune tolerance and immune escape." (PMID 40177401, 2025). "The clinical and pathological characteristics of GC patients depicted that high SNHG14 expression was significantly related to tumour size (≥ 5 cm), polypoid histologic type, tumour depth (T3/T4) and positive lymph node metastasis." (PMID 40521987, 2025). "After removing the tumour tissues, compared to the sh‐NC group, the tumours from the sh‐SNHG14‐1 group exhibited a decreased SNHG14 expression and elevated miR‐206 expression with a weakened FNDC3A expression." (PMID 40521987, 2025). "For instance, the knockdown of small nucleolar RNA host gene 14 (SNHG14) inhibited tumor cell proliferation and promoted apoptosis." (PMID 38948025, 2024). "LncRNA small nucleolar RNA host gene 14 (SNHG14) served as a tumor promoter in diffuse large B cell lymphoma (DLBCL)." (PMID 37767098, 2023). "Namely, SNHG14 was downregulated in the analyzed by qPCR set (logFC (binary logarithm of expression level fold change (tumor vs. normal)) = −1.1)." (PMID 35453574, 2022). "The NCBI GEO profiles (GDS3319/1455087_at) from a published study using a mouse model of papillary thyroid tumors indicates a significant increase in the SNHG14 transcript expression in the tumor versus normal tissue." (PMID 36672838, 2022). "Another research group reported that SNHG14 contributed to tumor cell malignant cells by increasing poly(A) binding protein cytoplasmic 1 (PABPC1) expression through H3K27 acetylation." (PMID 34631721, 2021). "To further explore the correlation between miR-876-5p and SNHG14, we performed spearman’s correlation analysis and the result demonstrated that miR-876-5p expression was negatively correlated with SNHG14 expression in tumor tissues (r = − 0.4679, P = 0.0091)." (PMID 33485374, 2021). "We found that SNHG14 expression was significantly upregulated in CRC tissues compared with adjacent non-tumor tissues." (PMID 34234865, 2021). "We found that high SNHG14 expression was strongly correlated with tumor stage, tumor size and distant metastasis." (PMID 34234865, 2021). "Emerging evidence revealed the expression of SNHG14 in tumor cell lines and the effect of knockdown or overexpression of this lncRNA on tumor cell malignant characteristics such as proliferation, invasion, migration, apoptosis, and drug resistance." (PMID 34631721, 2021). "In comparison with the si-SNHG14 + inhibitor NC group, the tumor volume and weight in the si-SNHG14 + miR-211-3p inhibitor group was distinctly elevated (all P < 0.05)." (PMID 33482820, 2021). "Decreasing SNHG14 inhibited RB cell proliferation, migration, and invasion, promoted apoptosis in vitro, and suppressed tumor growth in mouse tumor xenograft models." (PMID 33986660, 2021). "Decreased SNHG14 or up-regulated miR-211-3p reduced the tumor volume and weight of nude mice with BCa, as well as promoted apoptosis and restrained proliferation of tumor cells." (PMID 33482820, 2021). "Recent research verified the involvement of lncRNA-small nucleolar RNA host gene 14 (SNHG14) in the mediation of trastuzumab responses via tumor cell extracellular exosomes." (PMID 34277408, 2021). "Researchers discovered that SNHG14 expression was elevated in BCa cells compared with non-tumour cells, which suggested a poorer prognosis." (PMID 33968736, 2021).